NAMPT (nicotinamide phosphoribosyltransferase)
Diseases named in the same sentence as NAMPT in open-access papers (continued):
Sharing a sentence is not in itself a finding about the gene and the disease.
tumor (continued). "By combining NAMPT inhibitors (e.g., FK866) and NQO1 bioactivatable drugs (e.g., β-lap, ARQ761) we exploit the reliance of PDA on rapid NAD+ synthesis, as well as the tumor-selective overexpression of NQO1 through the use of agents that are bioactivated to induce cell death." (PMID 25590809, 2015). "Accordingly, FK866 and other NAMPT inhibitors did not demonstrate sufficient tumor-selectivity to achieve clinical success as single agents." (PMID 25590809, 2015). "When extrapolating these findings to the in vivo situation, we expect that the magnitude of effects of FK866 will be dependent on a tumor-cell’s nutrient state and its capacity for NAD+ synthesis via different metabolic pathways (i.e. via de novo or salvage pathways, via NAPRT or NAMPT)." (PMID 24824795, 2014). "Besides, FK866, a selective NAMPT inhibitor, largely inhibited NLRP4-induced tumor cells apoptosis." (PMID 40087771, 2025). "Additionally, multi-omics analysis of PDAC tumors with paired non-cancerous adjacent tissues (NATs) in the Clinical Proteomic Tumor Analysis Consortium (CPTAC) cohort revealed that protein and mRNA expression levels of NAMPT are significantly higher in PDAC tumors than in NATs." (PMID 38625917, 2024). "Furthermore, unlike tumor cells, which mostly depend on NAMPT, normal cells can synthesize NAD+ through other biosynthetic pathways, such as nicotinic acid phosphoribosyltransferase (NAPRT)." (PMID 38448544, 2024). "Finally, there is increased interest in the role of NAMPT and NAD availability in the tumour microenvironment, and recent evidence suggests that it may enhance immune checkpoint inhibitor therapy." (PMID 38893173, 2024). "Instead, we propose that circulating NAR may compensate for NAMPT inactivation in NAMPTi-treated tumor cells, particularly in the absence of de novo NAD synthesis." (PMID 38092728, 2023). "In addition, the expression level of NAMPT was positively correlated with TNM and tumor stage." (PMID 35776198, 2023). "Similarly, we observed no change in the NAMPT expression in the Italian CCA patients’ tumor samples (T) compared to the normal and stromal area." (PMID 36899911, 2023). "Immunoblotting of lysates from each of these cell lines revealed that levels of CtBP1/2 and NAMPT were higher in PDAC cell lines compared with HPNE cells, suggesting that both CtBP and NAMPT enzymatic activities may be hyperactive in PDAC tumor cells compared with normal pancreatic ductal cells." (PMID 37707363, 2023). "However, in five clinical investigations using three specific NAMPT inhibitors and a total of 104 patients, no meaningful tumor remission was identified (FK866, CHS828, and GMZ1777)." (PMID 36899911, 2023). "As CtBP activity is directly correlated with the stoichiometric availability of cellular NAD, we determined whether NAMPT inhibition, which has been used as a strategy for cellular NAD depletion in a number of tumor types, can effectively lower NAD levels in PDAC cells." (PMID 37707363, 2023). "Notably, when NAMPT is depleted in salvage-dependent tumors, they can still maintain NAD supply through the alternative salvage pathway, and the dual gene inhibition of NMRK1 and NAMPT leads to more effective NAD reduction and significant tumor suppression in vivo." (PMID 35906622, 2022). "Inspired by research suggesting that exogenous PA could terminate tumor cell proliferation through “NAMPT-NAD+-histone” axis, we systematically investigated the expression of NAMPT, NAD+, and histones (H2A, H2B, and H4) in U251 cells after different treatments." (PMID 35864093, 2022). "Furthermore, the increased expression of NAMPT by influencing Sirt-1, vascular endothelial growth factor (VEGF), and matrix metalloproteinase (MMP) activity significantly stimulates angiogenesis and thus contributes to the progression of tumor development." (PMID 36233428, 2022).
tumor (continued). "Thus, tumours from tissues with high NAPRT expression will have higher NAPRT amplification, and conversely, tumours from tissues with low NAPRT expression will be dependent on NAMPT activity." (PMID 36078035, 2022). "Furthermore, in agreement with these authors, we showed that MM is a type of tumor completely addicted to NAMPT, without significant amplification of NAPRT, as reported in other tumors." (PMID 35272691, 2022). "It is not surprising to note that several tumor cells have a greater expression of NAMPT." (PMID 35008323, 2021). "By analyzing the gene expression profiles of these TCGA tumor samples using GSEA with respect to high vs. low NAMPT expression, we observed an increase in both pro-inflammatory (including IFNγ response genes), and pro-glycolytic signatures correlating with higher NAMPT expression." (PMID 33976173, 2021). "To investigate the implication of PAK4 and NAMPT in PNET therapy resistance and survival, we first evaluated the basal expression level of these two proteins in PNET cell lines (BON-1 and QGP-1) and patient-derived tumor tissue using Western blotting and RT-qPCR." (PMID 31795447, 2019). "Regrettably, no objective tumor remission in response to these NAMPT inhibitors was observed." (PMID 29541451, 2018). "To assess the magnitude of olaparib sensitivity, we used NAMPT siRNA in olaparib dose–response survival experiments, demonstrating that each of the siRNA species sensitized not only CAL51 cells but also a commonly used PARP inhibitor resistant tumour cell line, HeLa." (PMID 22933245, 2012). "Furthermore, mIHC analysis confirmed that AREG and EGFR/ERBB2, as well as NAMPT and ITGA5/ITGB1, were overexpressed in the PMC_P region, verified in clinical specimen suggesting that these LRPs play a critical role in mediating tumor initiation in the tipping point." (PMID 40976783, 2025). "However, the method of treatment should be carefully considered since NAMPT inhibition with small molecules might not be effective, depending on the individual molecular background of a tumor." (PMID 35628596, 2022). "However, NAMPT is not a complete oncogenic factor and can interact with sirtuins to regulate cell function, its tumor-suppressive effect may be related to this." (PMID 35906622, 2022). "The low levels of PRPP in the extracellular space make it difficult to hypothesize that the enzymatic activity of NAMPT is necessary to extrinsicate its cytokine role, although this might not be true in the tumor microenvironment (because of the presence of necrosis areas) or in vesicles." (PMID 32477131, 2020). "While in the absence of tumor the levels of G-CSF are low, we were interested to check the hypothesis whether the lack of type I IFNs still induce NAMPT-mediated changes in neutrophil development and differentiation, resulting in altered activation of these cells already in bone marrow." (PMID 31717318, 2019). "In addition, correlative studies describing the effects of NAMPT inhibition on tumor microenvironmental factors are currently lacking in the clinical literature but would be informative to further clinical development of this class of agents and should be pursued in future studies." (PMID 32010616, 2019). "Patients #5, #6, and #7 (without tumor samples) showed an overlap of four genes (SORL1, PTPRC, MIR6819, and NAMPT), while #6 and #7 also shared five genes (CELF2, EDEM3, SMCHD1, RAVER1, and CXCR1)." (PMID 39001407, 2024). "NAMPT was upregulated in C1498 but not in MC38 cells, suggesting tumor type dependency in the IFNγ-induction of NAMPT." (PMID 36900204, 2023). "Comparing the pattern of expression of the NAPRT and NAMPT genes in human tumour cells with nontumor cells, there is high variability in the levels of NAPRT mRNA and protein in tumour cells." (PMID 36078035, 2022).
tumor (continued). "In addition, to investigate the function of NAMPT clearly, we did not use the inhibitor FK866 when tumor cells were cocultured with PBMCs due to the possible effect of FK866 on the metabolism of PBMCs." (PMID 35776198, 2023). "However, in five clinical trials testing three specific NAMPT inhibitors (FK866, CHS828 and GMZ1777), no significant tumor remission was observed in a total of 104 patients." (PMID 27462772, 2016). "Moreover, TWEAK treatment selectively induced NAMPT expression in TNBC but not HER2 or ER-positive cell lines, correlating with the elevated levels of NAMPT in Fn14-high TNBC tumours relative to matched normal tissues." (PMID 38965263, 2024).
infection (21 papers, 2015 to 2025). The state of being infected such as from the introduction of a foreign agent such as serum, vaccine, antigenic substance or organism. "Infection with a ply deficient mutant of Spn D39 induced NAMPT gene expression to a similar extent as wild-type Spn D39." (PMID 37783679, 2023). "While we confirmed JAK-dependency of NAMPT upregulation in response to Spn D39 infection using the JAK inhibitor Ruxolitinib, repression of NMNAT1 was not JAK-dependent." (PMID 37783679, 2023). "We also tested the therapeutic potential of an anti- monomeric NAMPT antibody using the same infection model." (PMID 37457744, 2023). "Deletion of pneumolysin from Spn D39 rescued NMNAT1 expression in BEAS-2B after infection, while NAMPT expression remained unaffected." (PMID 37783679, 2023). "Our multi-omics approach revealed that in response to Spn D39 infection, NAMPT and NNMT are upregulated in bronchial epithelial BEAS-2B cells as part of a general, pro-inflammatory response." (PMID 37783679, 2023). "Additionally, the levels of NAM, NMN, and NAD+ increased, and the expression of the key enzyme NAMPT in the NAD+ salvage pathway increased in intestinal epithelial cells after infection with F. nucleatum." (PMID 39739648, 2025). "Nevertheless, NAMPT upregulation may play a role in maintaining NAD+ homeostasis during the early stages of infection, potentially buffering the increased NAD+ demand driven by Parp activation." (PMID 41362627, 2025). "Notably, NAMPT protein levels remained elevated at later stages of infection, with a 1.77-fold increase at 21 dpi (SD ± 0.45, p = 0.0237) and a 2.93-fold increase at 24 dpi (SD ± 2.57, p = 0.0052) compared to mock controls." (PMID 41362627, 2025). "Both bacteria induced a significant upregulation of NAMPT expression 16 h post-infection." (PMID 37783679, 2023). "Additionally, RGS2 expression was strongly correlated with PTGS2, IL1B, CXCL8, NAMPT and other inflammation markers with substantial upregulation in early infection." (PMID 36143181, 2022). "NAMPT is upregulated by stressful stimuli including infection and pro-inflammatory cytokines." (PMID 25926556, 2015). "In addition, NAMPT is more likely to be secreted into the serum in presence of an acute infection, and this is consistent with the elevated production of white blood cells, making NAMPT one of the marker proteins that can be used to identify inflammatory conditions." (PMID 37910477, 2023). "Notably, pharmacological inhibition of NAMPT enzymatic activity or knock-down of Nampt or Sirt6 result in increased viral replication revealing anti-viral roles for these metabolic regulators in infection." (PMID 30886604, 2019). "Here, the authors show that chronic tumor-derived G-CSF drives NAMPT/NAD-dependent neutrophil dysfunction from the progenitor stage, and that targeting this pathway restores infection control." (PMID 41387444, 2025). "To assess how this affects the infection process, we experimentally decreased NAD+ biosynthesis by knockdown of NAMPT or NMNAT1 prior to bacterial infections." (PMID 37783679, 2023). "NAMPT and NNMT mRNA were upregulated compared to untreated controls after both Spn D39 infection and stimulation with the bacterial cell wall component lipoteichoic acid (LTA) for 9 or 16 h." (PMID 37783679, 2023). "To assess the role of NAD+ biosynthesis during the infection process, we performed siRNA knockdowns of NAMPT and NMNAT1 48 h prior to infection with Spn D39 (MOI 1, 16 h)." (PMID 37783679, 2023). "Up-modulation was specific for NAMPT, while the other three NBEs, i.e., NAPRT, NMRK1, and QPRT, were unaffected by infection with BRAF V600E (heatmaps on the right)." (PMID 35272691, 2022). "Based on gene expression data as well as MHV cellular infection data, NAM, NAMPT activators, and NR have similar potential to be strongly protective in vivo." (PMID 33051211, 2020).
infection (continued). "FCPLJ treatment downregulated several inflammatory cytokine genes in the liver, including CCL6/MRP-1, CCL8/MCP-2, CCL12/MCP-5, CCL17/TARC, IL1R1, IL1RN/IL1Ra, NAMPT/PBEF1, and PF4/CXCL4, indicating its potential role in mitigating inflammation during infection." (PMID 40007026, 2025). "NAMPT expression was also upregulated during the course of infection, but this induction did not appear sufficient to counterbalance the NAD+ decline." (PMID 41362627, 2025). "Deletion of the capsule locus (Δcps) and the H2O2 producing pyruvate peroxidase (ΔspxB) did not influence NMNAT1 or NAMPT expression during infection." (PMID 37783679, 2023). "Additionally, NAMPT protein levels at later stages of infection remain comparable to those observed at 12 dpi, with no further upregulation." (PMID 41362627, 2025). "However, while in accordance with the literature inhibition of JAK signaling by Ruxolitinib40 reduced NAMPT expression after Spn D39 infection, expression of NMNAT1 was not affected." (PMID 37783679, 2023). "To determine whether interference with the host NAD+ metabolism is a general process affecting bacterial infections, we performed BEAS-2B infections with Streptococcus agalacticae (S.aga) and non-typeable Haemophilus influenzae (NTHi) and determined the resulting expression of NAMPT and NMNAT1." (PMID 37783679, 2023). "On the other hand, NAMPT protein expression remains elevated during the later stages of infection and does not increase further alongside the rise in CD38 expression and activity, suggesting that NAMPT induction alone is insufficient to prevent the NAD+ decline in ZIKV-infected brains." (PMID 41362627, 2025).
metabolic disorders (19 papers, 2010 to 2025). "Higher levels of extracellular NAMPT, also known as visfatin, are associated with metabolic disorders." (PMID 32595600, 2020). "NAMPT showed a broad spectrum of effects in a number of diseases including metabolic disorders, inflammatory diseases, aging and so on." (PMID 35012648, 2022). "It has been suggested that increased levels of NAD+ via NAMPT could represent a protective strategy against the effects of metabolic disease." (PMID 35712781, 2022). "Visfatin, also known as NAMPT, is a key regulator of nicotinamide adenine dinucleotide (NAD) metabolism that is involved in the pathophysiology of metabolic disorders and cancer cell metabolism." (PMID 41036084, 2025). "More importantly, FK866 and quercetin consistently corrected NAD+ metabolic disorders, including expressions of NMNAT1, NAPRT, and NAMPT as well as NAD+ and NAD+/NADH levels both in vitro and in vivo." (PMID 35408818, 2022). "During various metabolic disorders, the level of NAD decreases, and thus, NAMPT regulates cell metabolism by affecting the activity of NAD-dependent enzymes." (PMID 34776833, 2021). "Among the metabolic disorders involved in this syndrome, NAD metabolism was shown to be altered in skeletalmuscle, with an important role for the NAMPT enzyme recycling the nicotinamide precursor." (PMID 30283350, 2018). "The activation of the NAMPT/NAD + /SIRT1 signaling pathway has been shown to optimize bile acid composition and decrease the production of proinflammatory cytokines, thereby ameliorating metabolic disorders in MASH model animals." (PMID 40807240, 2025).
cardiovascular diseases (8 papers, 2013 to 2024). "NAMPT is essential in fundamental physiological functions; however, a pathophysiological increase of NAMPT levels is implicated in the development of many cardiovascular diseases." (PMID 38898303, 2024). "Actually, bioinformatics and external validation suggest that downregulation of RASD1/NAMPT may be an important mechanism for the increased risk of cardiovascular disease in women with HCM." (PMID 39535387, 2024). "This abnormal cardiac energy metabolism and oxidative stress damage associated with downregulated NAMPT expression may partially explain why women with HCM are at a higher risk of cardiovascular disease compared to men." (PMID 39535387, 2024). "The analysis found that serum concentrations of NAMPT were much higher in patients with cardiovascular disease than in healthy individuals." (PMID 39513038, 2024).
bacterial infection (6 papers, 2015 to 2025). "The structural similarity between NAMPT and the cluster L phage protein suggests the potential for counteracting abortive bacterial infections involving NAD+ depletion, although the precise functional role is yet to be determined." (PMID 40728297, 2025). "The transcriptional regulation and blood/lung protein expression of NAMPT is highly induced by multiple ARDS-relevant stimuli including bacterial infection, shock, trauma, hypoxia, and excessive mechanical stress." (PMID 35705899, 2022). "First, both NAMPT transcriptional regulation and blood/lung protein expression, are highly induced by DAMP- and ARDS-relevant stimuli such as bacterial infection, hypoxia, shock, trauma and excessive ventilator-induced mechanical stress with plasma eNAMPT levels a biomarker for human ARDS severity." (PMID 35027578, 2022).